APOBEC3B (apolipoprotein B mRNA editing enzyme catalytic subunit 3B)
Diseases named in the same sentence as APOBEC3B in open-access papers (continued):
Sharing a sentence is not in itself a finding about the gene and the disease.
Sepsis (1 paper, 2024). Sepsis is defined as life-threatening organ dysfunction caused by a dysregulated host response to infection. "We performed a Mann-Whitney U test to evaluate the differential expression of the three genes (EIF1AY, APOBEC3B, and GUSBP3) in E. coli- and S. aureus-induced sepsis groups." (PMID 38968271, 2024).
skin cutaneous melanomas (1 paper, 2022). "The high-frequency APOBEC3B changes were principally mutations and amplifications in some tumors, such as uterine corpus endometrial carcinomas or cutaneous melanomas." (PMID 35918642, 2022).
cancer (177 papers, 2013 to 2026). A tumor composed of atypical neoplastic, often pleomorphic cells that invade other tissues. "Over the past 10 years, numerous studies have linked the mutagenic activities of APOBEC3A and APOBEC3B to the generation of mutational signatures observed in over 50% of human cancers." (PMID 40143363, 2025). "APOBEC3A and APOBEC3B encode DNA editing enzymes with anti-viral roles that generate somatic mutations in cancer." (PMID 39548236, 2025). "In some cancers a higher APOBEC3B expression was found to be associated with less immune cell infiltration in adrenocortical carcinoma and gastric cancer." (PMID 41373684, 2025). "The induced hyper-mutations of long stretches of single-strand DNA (ssDNA) formed during BIR (with APOBEC3A and APOBEC3B being the major mutators) through deamination, foster genome instability in cancer cells, a phenomenon referred to as ‘Kataegis’." (PMID 39910169, 2025). "Two APOBEC DNA cytosine deaminase enzymes, APOBEC3A and APOBEC3B, generate somatic mutations in cancer, thereby driving tumour development and drug resistance." (PMID 39548236, 2025). "In details, patients with high APOBEC3B expression detected in tumors had over two times higher risk of cancer progression than those with lower levels of this protein." (PMID 38907809, 2025). "The continuous expression of oncoprotein E6 seems to be pivotal for APOBEC3B overexpression in HPV-associated cancers." (PMID 38907809, 2025). "Two APOBEC (apolipoprotein-B mRNA editing enzyme catalytic polypeptide-like) DNA cytosine deaminase enzymes (APOBEC3A and APOBEC3B) generate somatic mutations in cancer, driving tumour development and drug resistance." (PMID 38496447, 2024). "Antiviral DNA cytosine deaminases APOBEC3A and APOBEC3B are major sources of mutations in cancer by catalyzing cytosine-to-uracil deamination." (PMID 38499542, 2024). "Together, our study provides evidence that APOBEC3A and APOBEC3B can generate distinct mutation landscapes in cancer genomes, driven by their unique substrate selectivity." (PMID 38499542, 2024). "Increased expression of APOBEC3B in individuals with cancer is associated with higher survival in TCGA, indicating that a more robust response to viral infection is correlated with a better prognosis." (PMID 39672307, 2024). "This study provides evidence that APOBEC3A and APOBEC3B can generate distinct mutation landscapes in cancer genomes, driven by their substrate selectivity." (PMID 38499542, 2024). "Among the seven members of the human APOBEC3 family, the enzymatic activity of APOBEC3B (A3B) has been implicated as a prime source of mutagenesis in multiple human cancers." (PMID 36766673, 2023). "The antiviral DNA cytosine deaminase APOBEC3B has been implicated as a source of mutation in many different cancers." (PMID 36865194, 2023). "The cytidine deaminases APOBEC3A (A3A) and APOBEC3B (A3B) are prominent mutators of human cancer genomes." (PMID 37532520, 2023). "APOBEC3B is also implicated in numerous cancers where it is responsible for the introduction of clustered mutations into the cellular genome." (PMID 36745676, 2023). "The antiviral DNA cytosine deaminase APOBEC3B has been implicated as a source of mutation in many cancers." (PMID 37797615, 2023). "Further implicating APOBEC3A as a predominant mutator, an APOBEC3B germline deletion that generates a chimera of the APOBEC3A coding region fused to the 5′ UTR of APOBEC3B has been associated with more APOBEC-induced mutations in some cancers." (PMID 36978147, 2023). "The single-stranded DNA cytosine-to-uracil deaminase APOBEC3B is an antiviral protein implicated in cancer." (PMID 37735199, 2023). "More recently, it has been shown that APOBEC3A is a more potent mutagenic agent than APOBEC3B, and that APOBEC3A signatures are far more frequent in human cancers than APOBEC3B-attributed mutations." (PMID 36980505, 2023).
cancer (continued). "Aberrant expression of APOBEC3B can generate several C>U or C>T mutations in the genome that drive cancer development." (PMID 36831487, 2023). "Future work will be necessary to dissect the mechanisms of APOBEC3 mutagenesis in cancers exhibiting an enrichment of genome-wide or clustered cytosine mutations in APOBEC3B-favoured RTCA motifs." (PMID 35859169, 2022). "APOEBC signature, which is derived from APOBEC3A and APOBEC3B cytosine deaminase activities, is one of the most common mutation signatures in different types of cancer, and it has been reported to be associated with tumorigenesis and drug resistance." (PMID 36439454, 2022). "Our results demonstrate that APOBEC3A expression, activity and mutagenesis can be increased by the loss of APOBEC3B in some cancer cell lines." (PMID 35859169, 2022). "Among candidate APOBEC3 enzymes, expression of APOBEC3B is the highest in cancer and moderately correlates with APOBEC3-associated mutational burdens." (PMID 35859169, 2022). "As APOBEC3B has been shown to be associated with mutations in genomic DNA, tumorigenesis, and drug resistance, it is a potential therapeutic target for cancer treatment." (PMID 35592333, 2022). "In contrast, APOBEC3B is only weakly expressed in normal tissues but thought to be the source of somatic mutations that drive tumor development within cancer cells." (PMID 36497451, 2022). "There is accumulating evidence that APOBEC3A and 3H are equally or even more potent mutators in cancers than APOBEC3B." (PMID 36970060, 2022). "For example, based on XCELL algorithm, the expression level of APOBEC3B in BRCA was negatively correlated with the infiltration level of cancer-associated fibroblasts (R = –0.316, P = 1.85e–24)." (PMID 35918642, 2022). "APOBEC3B is among the most widely studied factors related to G/C-to-A/T mutations in various human cancers." (PMID 35592333, 2022). "We performed in vitro experiments to determine cytidine deamination activity of APOBEC3B against oligonucleotides corresponding with genomic sequences that give rise to variants of high cancer effect size." (PMID 35872531, 2022). "In the UCSC Xena, pan-cancer analysis revealed a positive relationship between APOBEC3B (A3B) and tumor mutational burden (R = 0.28, P < 0.001) and microsatellite instability (R = 0.12, P < 0.05)." (PMID 36245972, 2022). "Recent evidence has linked the over-expression of APOBEC3B with various human cancers, including CRC, highlighting its possible contribution to genomic instability and kataegis." (PMID 34316699, 2021). "In particular, several studies strongly indicate that the nuclear-localized family member APOBEC3B (A3B) is a significant source of ongoing mutations in multiple human cancers, including those of the breast, head/neck, lung, bladder, and cervix." (PMID 33921405, 2021). "The associations of APOBEC3B deletion with the risk of cancers in European population are controversial." (PMID 34880864, 2021). "Second, there is considerable evidence from previous studies regarding correlations between total non-synonymous mutation of cancer-associated genes and mRNA expression of APOBEC3B." (PMID 33925044, 2021). "In this study, we clarified that IR induces APOBEC3B expression in cancer cells, and that APOBEC3B enhanced the radiation-induced mutation frequency." (PMID 32880638, 2020). "APOBEC3B, an anti-viral cytidine deaminase which induces DNA mutations, has been implicated as a mediator of cancer evolution and therapeutic resistance." (PMID 32034147, 2020). "A correlation between APOBEC3B expression level and the number of mutations in genomes was revealed using cancer cells." (PMID 33322756, 2020). "In particular, APOBEC3B expression is upregulated in multiple cancer types, is associated with the burden of signature C to T mutations, and with poor prognosis and therapeutic resistance." (PMID 32034147, 2020).
cancer (continued). "Although there is poor correlation between APOBEC3B expression levels in normal tissues and cancer risk, increased APOBEC3B expression is predicted to promote mutations in cancer cells." (PMID 32880638, 2020). "The present study reveals that APOBEC3B, a known oncogene, plays a role in radiation-induced mutation in cancers." (PMID 32880638, 2020). "The DNA cytosine deaminases APOBEC3A and APOBEC3B have emerged from cancer genomics studies as drivers of mutation in cancers and tumor heterogeneity." (PMID 32532990, 2020). "APOBEC3B is a cytosine deaminase that converts cytosine to uracil and causes an accumulation of C to T signature mutations in cancer genomes." (PMID 32648895, 2020). "Targeting UNG has been suggested to cause synthetic lethality in the many cancer cells that have high APOBEC3B levels (e.g. bladder, cervix, lung, breast, and head and neck cancers)." (PMID 32648895, 2020). "Many cancers overexpress APOBEC3B or harbor high kataegis mutational signatures conforming to deamination by the APOBEC/AID family of cytidine deaminases." (PMID 32264925, 2020). "To better understand the cancer risk posed by radiation and the development of radiation therapy resistant cancer cells, we investigated the involvement of the cancer risk factor, APOBEC3B, in the generation of radiation-induced mutations." (PMID 32880638, 2020). "APOBEC3B is found to be upregulated in various cancer types and acts as a leading candidate for cancer mutator, such as breast cancer, non-small-cell lung cancer, and serous ovarian carcinoma." (PMID 32775421, 2020). "APOBEC3A and APOBEC3B overexpression has been associated with localised C-to-T and/or C-to-G hypermutations termed “kataegis” in a number of cancers, suggesting that these signatures are important in cancer mutagenesis." (PMID 31547885, 2019). "Using a recombinantly expressed and purified preparation of full-length APOBEC3B—the APOBEC3 member most closely associated to human cancers—we tested its activity on two 25-mer substrates mimicking the DNA sequence surrounding the E542 and E545 sites." (PMID 30647454, 2019). "This advance opens the door to rigorously testing APOBEC3B as a cancer biomarker through protein-level association studies between APOBEC3B IHC levels and clinical outcomes including treatment responses and survival." (PMID 31544853, 2019). "By deconvolution of levels of different cell types in tumour admixtures, we demonstrate that APOBEC3B (A3B), the primary candidate as a cancer mutagen, shows little association with immune cell types compared to its paralogues." (PMID 30624727, 2019). "APOBEC3B-related mutational process fuels cancer evolution and treatment resistance, and still remains a big challenge for NSCLC treatment." (PMID 29695832, 2018). "The deaminase APOBEC3B is expressed in these cancers and causes mutations under replication stress; however, the mechanisms by which APOBEC3B mediates deamination and its association with genomic disorders are still unclear." (PMID 30417129, 2018). "Increased APOBEC3B gene expression, germline polymorphisms in the APOBEC3 genome region, and higher degree of abundance of APOBEC3B mutational signatures have been associated with increased cancer risk and patient survival." (PMID 29642934, 2018). "Through combined cancer genomic mutation analysis and gene expression analysis, here we identified a significant correlation among APOBEC3B expression and immune gene expression, tumor immunotherapy response." (PMID 29695832, 2018). "In many cancers, APOBEC3B increases the mutation load, generating clusters of closely spaced, single-strand-specific DNA substitutions with a characteristic hypermutation signature." (PMID 29642934, 2018). "Two members of the APOBEC family, APOBEC3A and APOBEC3B, contribute substantially to mutations in cancers by deaminating cytosines in the TpCpW context." (PMID 30514953, 2018).
cancer (continued). "The APOBEC3B (A3B) single-stranded DNA (ssDNA) cytosine deaminase has important roles in innate immunity but is also a major endogenous source of mutations in cancer." (PMID 29234087, 2017). "HPVs increase the activity of the cell cycle enzyme APOBEC3B which in turn causes genomic instability and increased risk of breast and other cancers." (PMID 29075317, 2017). "Logistic regression was used to derive odds ratios (ORs) and 95% confidence intervals (CIs) for the associations between the APOBEC3B deletion and cancer risk." (PMID 29100317, 2017). "Genetic, cellular and biochemical studies have demonstrated that APOBEC3B-catalyzed genomic uracil lesions are responsible for a large proportion of both dispersed and clustered mutations in multiple distinct cancers." (PMID 28572915, 2017). "Recent genome-wide sequencing data showed that apolipoprotein B mRNA editing catalytic polypeptide-like 3B (APOBEC3B) is a key molecular driver inducing mutations in multiple human cancers." (PMID 28572915, 2017). "An in-depth analysis has shown that the APOBEC3B mutation signature is specifically enriched in at least six types of cancers, including those of the cervix, breast, lung (adeno and squamous cell), head and neck, and bladder." (PMID 28572915, 2017). "In this review, we will discuss the biological function of APOBEC3B, its tumorigenic role in promoting mutational processes in cancer development and the clinical potential to develop novel therapeutics by targeting APOBEC3B." (PMID 28572915, 2017). "The association of the APOBEC3B deletion with cancer has been analyzed within eleven case-control studies conducted in populations of different ethnicities, different cancer types and different sizes [published and available in PubMed up to February 2017." (PMID 29100317, 2017). "It indicates that much more has to be done to explain the role of the APOBEC3 genes and the APOBEC3B deletion in the induction of somatic mutations in cancer." (PMID 29100317, 2017). "Recent studies have revealed that APOBEC3B is a significant contributor to the somatic mutation burden among several cancer types." (PMID 27977754, 2016). "Meanwhile, the strong correlation of somatic base-substitution mutation with APOBEC3B mRNA levels in cancer samples has implicated APOBEC3B as an enzymatic source inducing the C-to-T somatic mutations." (PMID 26682542, 2015). "A recent study on the comprehensive genome sequencing of cancer revealed that the apobec3b protein was associated with carcinogenesis in multiple cancers, including lung cancer." (PMID 25621070, 2015). "APOBEC3B is a newly identified source of mutation in many cancers, including breast, head/neck, lung, bladder, cervical, and ovarian." (PMID 26544511, 2015). "Independent studies have since implicated APOBEC3B mutagenesis in other types of cancer, including head/neck, lung, bladder, cervical, ovarian, and as many as 16 out of 30 cancers examined to date." (PMID 25848704, 2015). "APOBEC3B is the most likely cause of a large fraction of both dispersed and clustered cytosine mutations in six distinct cancers." (PMID 25071824, 2014). "Analysis of data pertaining to breast and lung cancer sequencing and expression suggested that it is specifically APOBEC3B that causes mutations in these types of cancer." (PMID 24748981, 2014). "At least three recent reports have suggested the involvement of aberrant APOBEC3B deaminase activity as a frequent cause of SBSs in cancer." (PMID 24705290, 2014). "The mechanism of such a high mutation rate in this particular patient is not clear, but such a C > T mutation pattern is consistent with APOBEC3B-mediated mutagenesis observed in other types of cancers." (PMID 25159915, 2014). "With respect to mutations at YC:GR sites, the gene expression data on APOBEC3B enzymes provide strong support for a role in cancer mutagenesis through U:G mismatch intermediates, as in the case of SHM." (PMID 24705290, 2014).